ENSG00000269877 (novel transcript)
Synonyms: LOC124904767
Gene: Long non-coding RNA gene on chromosome 19 (53,787,022 to 53,788,212, reverse strand). Ensembl gene ENSG00000269877.
Gene Ontology:
Biological process: miRNA-mediated post-transcriptional gene silencing